CA4 (carbonic anhydrase 4)
Diseases named in the same sentence as CA4 in open-access papers (continued):
Sharing a sentence is not in itself a finding about the gene and the disease.
tumor (continued). "Simultaneously, CA‐4 and ES‐Cu jointly evoked the release of DAMPs signaling molecules such as CRT, HMGB1, and ATP, reversing the immunosuppressive tumor environment, which in turn triggered ICD and activated the T‐cell‐mediated immune response, thus further enhancing the anti‐tumor efficacy." (PMID 40323152, 2025). "Of the four drugs tested in this study, only CA-4 and eribulin induced RhoA kinase activity in tumor pericytes suggesting a shared, non-mitotic pathway which we identified as vascular MEK/ERK suppression." (PMID 40140727, 2025). "Taken together, our results, along with previous findings, suggest a clear selectivity of CA-4 cytotoxicity toward tumor cells compared to non-dividing healthy lymphocytes, with proliferating lymphocytes being more sensitive." (PMID 39766242, 2024). "Poly(L-glutamic acid)-g-methoxy poly(ethylene glycol)/Combretastatin A4 (CA4)/BLZ945 nanoparticles (CB-NPs) possess the dual capability of CA4 (targeting blood vessels to induce tumor necrosis) and BLZ945 (inducing M2 macrophage apoptosis), thereby inhibiting tumor growth." (PMID 38375454, 2024). "DOX and CA4-dual-loaded PDA@PLGA-co-delivered NPs (PDA@PLGA/DC NPs) showed a tendency to accumulate within tumors and could be internalized by tumor cells to release drugs in acidic organelles." (PMID 37176991, 2023). "CA4-NPs destroyed the established tumor blood vessels and induced extensive tumor necrosis, and SOR reduced VEGF-A-induced angiogenesis to further inhibit tumor proliferation and exert a synergistic effect with CA4-NPs." (PMID 33859758, 2021). "The nanoplatform achieved an “attack + guard” antitumor strategy, in which CA4 inhibit growth of tumor by blocking nutrients and oxygen supplies, while PB- mediated NIR irradiation could strongly attack most tumor cells." (PMID 34930293, 2021). "Furthermore, the administration of CA4/Pasp-DOX/PEG-Phis to collagen, a major extracellular matrix component, significantly reduced tumor angiogenesis compared with that of controls, showing a change in the TME." (PMID 33261219, 2020). "CA2 and CA4 occur in healthy human kidneys, whereas CA9 is only present in tumor tissue." (PMID 33276608, 2020). "MSNs-iRGD loaded with CA4 and DOX could accumulate at the targeted tumor site due to the prolonged blood circulation, which resulted in better targeting to the vessel wall." (PMID 31346334, 2019). "Among the synthesized compounds, derivative 3d (R1 = naphth-2-yl) was the most active as an inhibitor of tumor cell growth, with IC50 values ranging from 33 to 702 nM in the five cell lines examined but was comparable to CA-4 as an inhibitor of tubulin polymerization." (PMID 28406191, 2017). "At 10 μM CA4 and CTX were effective in reducing initial tumor volume by 18 respectively 20%." (PMID 26831010, 2016). "We showed that CA4 suppressed the expression of VEGF both in MCF-7 cells and HUVECs, suggesting that CA4 might inhibit tumor angiogenesis through both paracrine and autocrine VEGF mechanisms." (PMID 27338725, 2016). "In view of the in vitro anti-tumor activity, the anti-VM effect and the reported vascular disruptive effect of CA4, we suggest that NGR-SSL-CA4 is more effective in killing U87-MG cells, the VM formed by U87- MG cells as well as endothelial cells than SSL-CA4." (PMID 27283987, 2016). "When PALA reached the tumor site, the high level of intra-tumor GSH reduced the disulfide bond in PALA, resulting in the degradation of the polymer and subsequent in situ release of CA4, which had strong anti-cancer activity without causing systemic toxicities." (PMID 37452423, 2023). "Surprisingly, higher levels of CA4 were found in EBP samples in LUAD patients both preoperatively and after surgical removal of the tumor in the present study compared to control patients, indicating that CA4 might not be a good candidate for evaluating LUAD in EBP." (PMID 36544145, 2022).
tumor (continued). "The combination of CA4-NPs and DC101, therefore, successively disrupted and normalized tumor vasculature, simultaneously reducing the tumor burden, increasing the number of intratumoral CD8+ T cells, and successfully regulating the imbalance between CD8+ T cells and tumor burden." (PMID 33897892, 2021). "Most importantly, CA4-NPs were mainly distributed at the tumor site because of the triple target effects—enhanced permeability and retention (EPR) effect, acid-sensitive (pH = 5.5) effect to the tumor microenvironment (TME), and good selectivity of CA4 for central tumor blood vessel." (PMID 33933077, 2021).
cancer (69 papers, 2014 to 2025). A tumor composed of atypical neoplastic, often pleomorphic cells that invade other tissues. "For example, the anti-cancer drug combretastatin A4 (CA4) was covalently linked with single-walled carbon nanotubes (SWCNT) with a superior cell cycle arrest than the free CA4." (PMID 35582007, 2021). "TIME correlated with CA4 was displayed to uncover the underlying molecular mechanisms in these cancers." (PMID 32922550, 2020). "Lastly, we have shown that cancer cells deficient in the extrinsic pathway of apoptosis experience delayed cell death following treatment with CA4 or analogues." (PMID 28253265, 2017). "Despite chemical ablation of mitotic arrest being able to rescue cancer cells, we have uncovered preliminary evidence that the extrinsic pathway of apoptosis may also play a role in CA4- linked cell death." (PMID 28253265, 2017). "This differential action between normal and cancer cells highlights the selective anticancer effect of CA-4." (PMID 39766242, 2024). "Compounds 6a, 6c, 6e–g, 11a, and 11c potently inhibited tubulin polymerization, with activities higher or comparable to that of reference compound CA-4, correlating well with their antiproliferative potency against all tested cancer cell lines." (PMID 39062759, 2024). "Combretastatins, including CA-4, exacerbate this stress by driving cancer cells beyond their threshold for tolerable DNA damage, leading to apoptosis." (PMID 39766242, 2024). "Previous studies documented the most potent antiproliferative activity of CA-4 against various cancer cell lines, with IC50 values ranging from 0.08 to 35.6 μM and from 0.36 to 7.08 μM." (PMID 39766242, 2024). "CA-4 exhibited lower cytotoxicity in human PBMCs compared to cancer cells, inhibited ROS production, and showed antioxidant and antigenotoxic properties, providing insight into its potential therapeutic efficacy and safety." (PMID 39766242, 2024). "CA-4 can also exacerbate DNA damage in cancer cells, and this exacerbated DNA damage, in conjunction with their impaired DNA repair mechanisms, increases their susceptibility to apoptosis." (PMID 39766242, 2024). "CA-4 (IX) is known to be an outstanding anticancer agent that has a selective targeting for cancer angiogenesis." (PMID 36790582, 2024). "By further increasing ROS production in cancer cells, CA-4 induces oxidative damage, which disrupts important cellular processes and ultimately leads to cell death." (PMID 39766242, 2024). "In this study, we demonstrated significant differences in sensitivity to CA-4 between healthy, normal cells and cancer cells." (PMID 39766242, 2024). "Based on this mechanism of action, CA4 arrests the cell cycle in metaphase and triggers apoptosis, resulting in a high toxicity profile against different human cancer cell lines." (PMID 37111767, 2023). "Similar results were found with a series of new 3-alkyl-1,5-diaryl-1H-pyrazoles synthesized as CA4 analogues and evaluated for antiproliferative activity against three human cancer cell lines." (PMID 37111767, 2023). "Our previous studies focused on the optimisation of the activity of CA-4 derivatives against cancer cells." (PMID 36838705, 2023). "Docking simulation of the CA-4 compound, as a colchicine-analogous and well-known anti-cancer candidate, formed two HBs with V-181 and C-239 within C- and D-tubulin, respectively." (PMID 36546947, 2022). "Our results showed that the PSA of the most synthesized structures was biomimetic to CA-4, and similar chemical and biological properties were observed against Hep3B cancer cell line." (PMID 36546947, 2022). "We also found that CA4-NP exhibits certain characteristics similar to paclitaxel-NP: inhibiting bulk cancer cell but enriching CSCs, and upregulating CSC-related YAP signal." (PMID 33414428, 2021). "Triazole imidazole, and pyridine-containing analogs of CA-4 are also reported with antiproliferative activity in human cancer cell lines." (PMID 33671674, 2021).
cancer (continued). "It is suggested to be a potential prognostic biomarker, while the correlations between CA4 and different cancers are indistinct." (PMID 32922550, 2020). "Because of its simple structure, hundreds of CA-4 analogs have been synthesized, with some having activity against paclitaxel-resistant cancer cells and some having different tubulin binding mechanism from that of CA-4 (e.g., cyclopropylamide analogs)." (PMID 32610496, 2020). "The differential mRNA expression of CA4 in various human cancers and paired normal tissues were compared on the basis of datasets released from the Oncomine and TIMER platform." (PMID 32922550, 2020). "Functional annotations and immune infiltration correlation were also investigated between CA4 and related cancers." (PMID 32922550, 2020). "Together, these findings highlight that CA-4 is an important clinical lead compound for cancer therapy." (PMID 32610496, 2020). "This review aims to focus attention on recently emerging research on CA-4 derivatives with strong potential for further development as clinically used anti-cancer agents." (PMID 31947889, 2020). "CA-4 shows strong cytotoxicity against a variety of cancer cells, including multidrug resistant cancer cell lines." (PMID 32033084, 2020). "Isocombretastatin A-4 (isoCA-4), an unexpectedly synthesized isomer of CA-4 found by Alami, exhibited a very strong inhibition on cancer cell growth similar to that of CA-4." (PMID 32155790, 2020). "In our study, CA4 mRNA expressions were found significantly lower in 15 kinds of cancers compared to corresponding normal tissues." (PMID 32922550, 2020). "These molecules possess higher antiproliferative activities against some cancer cell lines than the most representative combretastatin family member, i.e., CA-4." (PMID 30875859, 2019). "Overall, we obtained results using two independent small molecule inhibitors, which strongly suggest that CA4 functions primarily as a MTA to kill cancer cells in vitro." (PMID 28253265, 2017). "At the 48 hour time point, it was seen that CA4 and analogues possessed the ability to induce apoptosis in a variety of cancer cell lines." (PMID 28253265, 2017). "Although our preliminary work suggests that they require doses that are roughly 1000 times higher than CA4 for activity, they represent the first instances of anti-cancer CA4 analogues comprised of directly connected phenyl rings." (PMID 28253265, 2017). "Additional mechanistic evaluation of the biphenyl derivatives found that their anti-cancer activity is dependent on prolonged mitotic arrest, in a similar manner to CA4." (PMID 28253265, 2017). "It has been generally accepted that CA4 induces apoptosis in cancer cells in vitro through a mechanism dependant on the disruption of microtubule dynamism and prolonged activation of mitotic checkpoints." (PMID 28253265, 2017). "The vascular disrupting properties of CA-4 and related compounds represent a new approach for cancer treatment." (PMID 27216165, 2016). "A water soluble disodium phosphate derivative of CA-4 (CA-4P, fosbretabulin) has shown promising results in human cancer clinical trials, thus stimulating significant interest in a variety of CA-4 analogues." (PMID 24962392, 2014). "Interestingly, CA-4 has shown opposite effects in cancer cells by significantly increasing ROS levels, thereby exceeding the threshold for oxidative stress." (PMID 39766242, 2024). "Interestingly, although CA-4 disrupts antioxidant defenses in cancer cells, it has also been reported to exhibit potent antioxidant properties compared to other analogous compounds." (PMID 39766242, 2024). "In addition, CA-4 has been investigated for its effects on the production of reactive oxygen species (ROS) in cancer cells." (PMID 39766242, 2024).
cancer (continued). "In relation, compound X, indole-based CA-4 analog, showed good antiproliferative activities against various cancer cell lines; also, it displayed acceptable anti-tubulin activity compared with positive control CA-4 with IC50 values of 18 and 0.54 μM, respectively." (PMID 36790582, 2024). "CA-4 further increases ROS levels and exacerbates oxidative stress in cancer cells." (PMID 39766242, 2024). "CA4 is a natural compound known for its potent anti-cancer properties." (PMID 38543094, 2024). "The aim of this study is to evaluate the in vitro bioactivity of CA-4 in human PBMCs, focusing on its antigenotoxic and antioxidant properties, while comparing its cytotoxic potency against PBMCs, cancer cell lines (JAR and HeLa), and the normal trophoblast cell line HTR-8/SVneo." (PMID 39766242, 2024). "In addition, although several compounds, such as 6b, 6g, 11c, and 11e showed lower antiproliferative activity on MDA-MB-231 cancer cells when compared with CA-4, they were comparable to or more potent than CA-4 as inhibitors of tubulin assembly." (PMID 39062759, 2024). "In our cases of PDy, we speculate that inflammation promotes the production of CA4, leading to collagen degeneration and desmoplasia and, in advanced cases, allowing for the dysplastic progression to infiltrate the carcinoma by altering the ECM." (PMID 39273632, 2024). "CA-4-based codrugs (or mutual prodrugs) have recently been demonstrated to improve the therapeutic profile of clinically used drugs such as doxorubicin, floxuridine and tegafur, and they have achieved targeted delivery of drugs to cancer tissues." (PMID 37513912, 2023). "CA4 was also found to be significantly different, and low expression of CA4 can promote proliferation of cancer cells, whereas overexpression can suppress proliferation of cancer cells." (PMID 36544145, 2022). "CA-4 possesses anti-cancer activity against multiple human cancer cell lines." (PMID 35628467, 2022). "However, in our study we observed a lower expression in CA4 N-glycans in carcinoma compared with dysplastic region." (PMID 35326703, 2022). "Taken together, our results show that paclitaxel and CA4 are important to decrease the viability of bulk cancer cells, CA4 and verteporfin in combination significantly suppress angiogenesis, and verteporfin reduces CSC enrichment following paclitaxel and CA4 treatment." (PMID 33414428, 2021). "Therefore, CA4 is suggested to provide a novel biomarker for diagnosis, immunotherapy and prognosis in these cancers." (PMID 32922550, 2020). "The relationships between CA4 mRNA expression and prognosis of cancer patients were investigated." (PMID 32922550, 2020). "It mirrors CA-4’s biological mechanism of action and both phenstatin and its corresponding water-soluble prodrug salt demonstrate pronounced cytotoxicity against human cancer cell lines." (PMID 31947889, 2020). "CA-4 is typically observed to inhibit 50% of cancer proliferation within a dose range of 1–10 nM." (PMID 31947889, 2020). "Antiproliferative successes are good with similar anti-cancer potencies to CA-4." (PMID 31947889, 2020). "It has reduced toxicity and improve anti-cancer activity relative to CA-4." (PMID 31947889, 2020). "In addition, CA4 is possible to play an important part in immune cell infiltration among these five cancers." (PMID 32922550, 2020). "In present study, we explored prognostic significance of CA4 among pan-cancers." (PMID 32922550, 2020). "Only the cis configuration of CA-4 and other stilbene derivatives possess anti-cancer bioactivity." (PMID 31947889, 2020). "Moreover, relative CA4 mRNA expression levels between different cancers and corresponding normal tissues were determined based on TCGA database using Student's t test." (PMID 32922550, 2020).